MMP3 (matrix metallopeptidase 3)
Diseases named in the same sentence as MMP3 in open-access papers (continued):
Sharing a sentence is not in itself a finding about the gene and the disease.
breast cancer (continued). "Concordant with this phenotype, mRNA expression of epithelial E-cadherin and ZO1 was enhanced, whereas transcription of mesenchymal genes (N-cadherin, Vimentin, Fibronectin, MMP3) was reduced in TBX2-depleted MDA-MB-435 and MDA-MB-157 breast cancer cells." (PMID 22844464, 2012). "To further address a possible role for MMPs in IL-17-dependent invasiveness of breast cancer cell lines, we assayed the supernatants from IL-17-treated and control MDA-MB231 and MDA-MB453 cells for the presence of MMP-2, MMP-3, MMP-9 and TIMP-1." (PMID 19014637, 2008). "Under these conditions, four secreted MMPs were identified: MMP-1, MMP-3, MMP-9, and MMP-13 and the membrane-anchored MMP, MT1-MMP in all 3 breast cancer cell lines (MDA-231 cells shown, results similar in all 3 breast cancer cell lines)." (PMID 15701164, 2005). "For association between MMP-3 and prognosis of breast cancer, one study indicated that MMP-3 did not impact on overall survival but a higher level of cellular expression of MMP-3 had a significantly poorer metastasis-free survival." (PMID 37188722, 2023). "In the present study, IL6, IL8, and MMP3, which have been highlighted for their pro‐tumorigenic activities of individual SASP factors in many studies, produced by LAP‐induced senescent breast cancer cells." (PMID 37792675, 2023). "Genetic silencing of MMP-3, also referred to as stromelysin-1, reduced tumor progression and angiogenesis in mouse models of BM-PCa, and MMP-3 has been shown to play a role in migration in other cancer types, including breast cancer and osteosarcoma." (PMID 37025604, 2023). "The role of matrix metalloproteinase-3 (MMP-3) and (MMP-7) in the pathogenesis of breast cancer (BC) has been demonstrated, suggesting that they may be considered as potential markers of this condition." (PMID 37048701, 2023). "Studies have shown that MMP3 can promote the metastasis of CRC, melanoma, and breast cancer." (PMID 36338624, 2022). "This interesting role in breast cancer may be due to the inhibition of TGF-β with subsequent activation of programmed cell death 4 (PDCD4), decrease of MMP-3 and MMP-9 and increase of cell adhesion." (PMID 34884877, 2021). "Overexpression of SCARA5 downregulated MMP-2, MMP-3 and MMP-9 in breast cancer cell." (PMID 33758617, 2021). "Numerous tumor-derived cytokines including granulocyte macrophage colony-stimulating factor (GM-CSF), thymic stromal lymphopoietin (TSLP), matrix metalloproteinase 3 (MMP-3) and matrix metalloproteinase 9 (MMP-9) have been reported to contribute to breast cancer progression." (PMID 32887217, 2020). "Furthermore, our previous investigation has indicated that rCTII can robustly decrease MMP-3 and MMP-9 expression in breast cancer." (PMID 33167431, 2020). "In this study, we reported that arctigenin, a bioactive compound from Arctium lappa L., could decrease tumor-promoting cytokines GM-CSF, MMP-3, MMP-9 and TSLP in breast cancer cells." (PMID 32887217, 2020). "Moreover, interference of cell contact-regulated communication by MMP3 and further cooperation with activated Rac1b is involved in EMT and plays a key role in early stages of breast cancer development." (PMID 30621237, 2019). "Interestingly, in a mouse mammary tumor model, TGF-β promoted the induction of EMT and translationally upregulated Mmp3 in an ALK5-dependent manner." (PMID 31434318, 2019). "MMP3 and MMP1 have a synergistic effect on breast cancer carcinogenesis." (PMID 30517191, 2018). "Although down-regulation of MMP-3 reduced lung cancer spontaneous metastasis, genetic ablation of MMP-3 did not significantly affect breast cancer metastasis was also documented." (PMID 26528698, 2015). "On the other hand, although MMP-3 was not prognostic when all breast cancers were considered, it was prognostic of poor outcome in basal-like breast cancers." (PMID 25633981, 2015).
breast cancer (continued). "Our findings show MMP-3/ROS-induced and NF-κB-mediated Snail transcription as a functional link between increased MMP expression in breast cancers and progression to metastasis that could be targeted for therapeutic response." (PMID 24811539, 2014). "In breast cancer, the targeted overexpression of activated MMP-3 in the mammary gland induces the transition of normal cells to malignant epithelial cells, suggesting that MMP-3 promotes mammary carcinogenesis." (PMID 24531055, 2014). "In prostate and breast cancer cells, matrilysin (MMP-7) and stromelysin (MMP-3) have been shown to generate a soluble 80-kDa fragment, and ADAM-10, a transmembrane protease, controls constitutive and regulated shedding of E-cadherin in cell cultures of keratinocytes and in vivo in mouse embryos." (PMID 18478055, 2008). "Our gene expression data also support a role in ST-3 activation of Wnt-signalling components, such as FZD7 and DVL3, which is in line with the activation of the Wnt pathway by ST-1/MMP-3 via E-cadherin cleavage, resulting in EMT and thus enhanced invasive properties of mammary tumour cells." (PMID 17233884, 2007). "Our observation of MMP-3 gene expression in the stroma of four out of six of the xenografts examined, and in particular in the Hs578T xenograft, further support a role for this MMP in breast cancer." (PMID 16430785, 2006). "Additionally, pTyr-PAK1-dependent secretion of MMP-3 may participate in the extracellular cleavage of E-cadherin leading to the EMT and increased invasion of breast cancer cells." (PMID 38660565, 2024). "Similarly, downregulation of neither Mmp3 nor Kdm6a had a significant effect on primary mammary tumour growth." (PMID 38926506, 2024). "In addition, several MMPs that contribute to the proteolysis of collagen-425,26, including MMP2, MMP3, MMP9, and MMP14, were upregulated in either lung fibroblasts exposed to breast cancer cell-conditioned media, or premetastatic lungs in metastatic primary tumor-bearing mice." (PMID 37903851, 2023). "According to the results obtained by our team on MMP-3 and MMP-7, they may appear to be useful as new biomarkers in the primary diagnosis of patients with early stage breast cancer (TNM stage I) and the most common subtypes—Luminal A and Luminal B HER2-negative." (PMID 37048701, 2023). "Furthermore, arctigenin intervention suppressed protein expressions and mRNA level of GM-CSF, MMP-3, MMP-9 and TSLP in breast cancer cells, suggesting that arctigenin decreases the secreted GM-CSF, MMP-3, MMP-9 and TSLP at the transcriptional level in breast cancer cells." (PMID 32887217, 2020). "Tumour cell MMP3 expression was reported to be a prognostic factor for poor survival in breast cancer, and MAP2 expression was shown to be significantly associated with pathological responses to neoadjuvant chemotherapy, regardless of breast cancer subtype." (PMID 29675884, 2018). "For instance, overexpression of a stromal proteinase-matrix metalloproteinase-3 (MMP3) in both mouse phenotypically normal mammary epithelial cells (Scp2) and the mammary glands of transgenic mice, results in a reactive stroma and eventually leads to infiltrative mammary tumors." (PMID 28640191, 2017). "Furthermore, a recent study showed that perioperative lidocaine IVA reduces the postoperative extracellular trapping of neutrophils, an immune and angiogenic factor, and the postoperative expression of MMP-3 in patients undergoing breast cancer surgery, regardless of the GA technique." (PMID 35223475, 2022). "Also MMP3 expression was connected to promoting rather than restricting mammary carcinoma." (PMID 33014872, 2020). "Results from this study strongly suggest that the increased expression of MMP-3 and uPA at the same time that a PAI-1 decrement in the same tissues might be an important step for development of metastasis towards lymphatic ganglia, as shown in Mexican breast cancer patients." (PMID 27975070, 2016).
breast cancer (continued). "The loss of MB increased the migration of hypoxic, but not normoxic, MCF7 breast cancer cells through the activation of the SMAD signaling pathway and upregulation of MMP3 expression." (PMID 36232784, 2022). "This retrospective cohort study shows the immunohistochemical expression levels of MMP-1, MMP-2, MMP-3, and MMP-9 in 154 women with breast cancer and 42 women without tumor disease." (PMID 34445715, 2021). "Five genes (MMP3, CDKN1A, RUNX1, TIMP2, CCND1) are common in cervical, ovarian, endometrial cancers, but not in breast cancer." (PMID 31205821, 2019). "Proteoglycans and MMP-3 in the ECM of radiologically dense breast tissue have already been shown, in the absence of breast cancer, to be similar to those expressed in breast tissue associated with breast cancer." (PMID 29514672, 2018). "In this study we evaluated genetic variation in MMP1, MMP2, MMP3, and MMP9 using data from a large collaborative case-control study of breast cancer in Hispanic and non-Hispanic white women (NHW) from the United States and Mexico." (PMID 23696797, 2013).
osteoarthritis (145 papers, 2008 to 2025). A noninflammatory degenerative joint disease occurring chiefly in older persons, characterized by degeneration of the articular cartilage, hypertrophy of bone at the margins and changes in the synovial membrane. "Another advantage of controlling MMP-3 levels is the reduced risk of osteoarthritis after ACL surgery, as is currently the case, where 45% of postoperative ACL reconstruction patients experience OA after 10 years." (PMID 40149932, 2025). "Osteoarthritis negatively affects the articular matrix whose mechanism is associated with the MMP-3 action." (PMID 40406605, 2025). "MMP-3, along with other MMPs, has been shown to affect tumor cell migration and invasion, but its improper activity has been linked mainly to osteoarthritis." (PMID 38003553, 2023). "Polymorphisms within MMP-3 gene have previously been reported to be associated with several complex musculoskeletal disorders such as osteoarthritis, frozen shoulder, and disc degeneration." (PMID 35172898, 2022). "Several of the significantly upregulated genes are associated with risk of lumbar disc degeneration and osteoarthritis assayed in humans or animal models, including Aspn, Dkk-3, and Mmp3." (PMID 31652254, 2019). "This MMP3 promoter polymorphism has been associated with osteoarthritis, lung cancer, and myocardial infarction." (PMID 29458338, 2018). "Similarly, upon testing a few catabolic genes implicated in osteoarthritis, we observed a significantly lower upregulation of MMP3 and ADAMTS4 in the hiChondrocytes and juvenile chondrocytes." (PMID 29096706, 2017). "Additionally, TNF-α cannot directly cause extracellular matrix degradation in osteoarthritis chondrocytes but rather induces chondrocyte production of MMP3 through TNF-α receptor P55, leading to degradation of the cartilage matrix and subsequent chondrocyte apoptosis." (PMID 37953787, 2023). "Furthermore, decreased proteoglycan loss in human OA cartilage with IL-37 via inhibition of MMP-3 expression and the protection of stem cells in an inflammatory osteoarthritis-like microenvironment for cartilage formation support IL-33 and IL-37 as potential therapeutics." (PMID 34842603, 2021). "Owing to the key role of MMP13 and MMP3 in osteoarthritis, these two genes were of significant interest." (PMID 40583170, 2025). "Prior clinical investigations reported that patients with RA have elevated serum and synovial fluid levels of MMP-1 and MMP-3 compared to osteoarthritis patients and normal ones, correlated to the levels of other disease activity markers." (PMID 40350466, 2025). "This is an unexpected result, as previous studies confirm the involvement of MMP-3 in bone degradation—such as in osteoarthritis." (PMID 39407715, 2024). "Among various MMPs, MMP-1, MMP-3, and MMP-13 are reported to demonstrate increased expression in osteoarthritis and are closely associated with its development." (PMID 38542192, 2024). "In vivo, the obese mice fed high-fat diets presented with osteoarthritis-like changes and increased the expression of Interleukin-1 Beta (IL-1B), Matrix metalloproteinase-3 (MMP-3) and leptin in temporomandibular joints." (PMID 37464321, 2023). "Previous studies have demonstrated that the CX3CL1/CX3CR1 axis is involved in cartilage destruction due to osteoarthritis by inducing MMP-3 secretion from synovial fibroblasts through c-Raf, MEK, ERK, and NF-κB pathways." (PMID 38283363, 2023). "Lower expression of MMP3, as a proteolytic enzyme which is well known in the development and spread of inflammatory diseases such as osteoarthritis, was especially observed in treatment group 4 using IHC staining." (PMID 35177103, 2022). "Genes such as Matrix metalloproteinase-3 (MMP3) are enzymes that are involved in the breakdown of extracellular matrix proteins, for example in disease processes such as osteoarthritis." (PMID 36143926, 2022).
osteoarthritis (continued). "The ectopic expression of GAS5 in human osteoarthritis chondrocytes elevates MMP-3 expression and reduces the contents of Collagen II and aggrecan." (PMID 34413821, 2021). "Previous studies were focused on a correlation between MMP-3 plasma levels and MMP-3 synovia levels for dogs suffering from osteoarthritis." (PMID 34677442, 2021). "MMP-1 and MMP-3 likely participate in cartilage destruction in rheumatoid arthritis and osteoarthritis." (PMID 32116759, 2020). "It was reported that MMP-3 is highly expressed in the synovial cells of osteoarthritis and can promote the proliferation of synovial cells and inhibit apoptosis." (PMID 33053109, 2020). "Other contributions to osteoarthritis from activities related to MMP-3 include MMP-3-mediated activation of MMP-1 and MMP-13." (PMID 32116759, 2020). "In our study, MMP-3 was found to be highly expressed in synovial cells of osteoarthritis in all OA groups." (PMID 33053109, 2020). "The measurement of plasma/serum MMP3 activity had been explored limitedly for some diseases such as osteoarthritis 21 and Alzheimer disease." (PMID 32922541, 2020). "Based on previous research and our data, we inferred that high expression of MMP-3 was closely related to the occurrence and development of synovitis and osteoarthritis." (PMID 33053109, 2020). "The results of western blot also showed that the average expression of MMP3 in 30 osteoarthritis patients was 132% higher than that of the healthy group, which confirmed that MMP3 was highly expressed in osteoarthritis group." (PMID 30560591, 2019). "In the two chips of GSE1919 and GSE55235, the average expression of MMP3 in the osteoarthritis group was 63.7% and 12.9% higher than that of the healthy control, respectively." (PMID 30560591, 2019). "Spontaneous secretion of some adipocytokines (MMP-3 and/or TNF, CCL2/MCP-1, IL-1Ra) was higher in osteoarthritis than rheumatoid ATs and probably caused by weaker anti-inflammatory treatment of OA patients." (PMID 30280295, 2019). "Other studies report that curcumin decreases inflammation in osteoarthritis synovial cells by inhibiting matrix metalloproteinase-3 (MMP3) expression." (PMID 31052496, 2019). "In this study, we predicted the differentially expressed gene MMP3 by means of chip analysis, and experimentally verified its high expression in osteoarthritis synovial cells through western blot and qRT‐PCR experiments." (PMID 30560591, 2019). "In this study, we mainly investigated the effects of MMP3 on synovial cells of osteoarthritis, and explored the regulating effects of curcumin on the expression of MMP3." (PMID 30560591, 2019). "The western blot results also showed that the average expression of MMP3 in synovial cells of osteoarthritis was 132% higher than that of the healthy group (P < 0.01)." (PMID 30560591, 2019). "Reanalyzing the expression of MMP3 in GSE1919 (n = 5) and GSE55235 (n = 10) showed that compared with normal synovial cells (healthy control group), MMP3 was highly expressed in the synovial cells of osteoarthritis (P < 0.05)." (PMID 30560591, 2019). "We studied the effect of naringenin on the transcriptional expression, secretion and enzymatic activity of MMP-3 in vivo in the murine monosodium iodoacetate (MIA) osteoarthritis model." (PMID 28355351, 2017). "We showed that DJH protected against OVX-induced osteoarthritis by preventing the decrease in articular cartilage, with reduced levels of MMP-3, MMP-13, and also proinflammatory cytokines in OVX rats with osteoarthritis induced by MIA." (PMID 29348767, 2017). "In osteoarthritis patients, MMP-3 promotes the degradation of bone matrix and stimulates bone tissue repair." (PMID 28445942, 2017). "We investigated the signaling pathway involved in CX3CL1-induced MMP-3 production in osteoarthritis synovial fibroblasts (OASFs)." (PMID 29268768, 2017). "Clearly, the mechanisms of how the MMP-3 gene contributes to osteoarthritis are complex, and need to be clarified." (PMID 29108328, 2017).